HERC2P2 (HERC2 pseudogene 2)
Synonyms: D15F37S3
Gene: Transcribed unprocessed pseudogene on chromosome 15 (22,495,570 to 22,579,813, forward strand). Ensembl gene ENSG00000276550.
Diseases named in the same sentence as HERC2P2 in open-access papers:
HERC2P2 is named in the same sentence as 3 diseases in open-access papers, as found by Europe PMC text mining. Sharing a sentence is not in itself a finding about the gene and the disease. The quoted sentences say what the papers report.
breast carcinoma (2 papers, 2020 to 2022). "HERC2P2 was recently identified as a component gene in a 10-gene panel of blood transcripts that classifies the risk of breast cancer." (PMID 33266355, 2020).
tumor (3 papers, 2020 to 2021). "Overexpression of HERC2P2 reduces migration and colony formation abilities and reduces tumor growth in vivo." (PMID 34947885, 2021).
HERC2P2 also shares sentences with these, for which no sentence is quoted: cancer (1 paper).